BRCA1 (BRCA1 DNA repair associated)
Diseases named in the same sentence as BRCA1 in open-access papers (continued):
Sharing a sentence is not in itself a finding about the gene and the disease.
cancer (continued). "The fact that CD8+ T cells were both enriched and clonally expanded in the BRCA1 mutation carriers suggests that there is an early adaptive immune response among the FTE cells in patients with a BRCA1 mutation, even before the development of cancer." (PMID 36076202, 2022). "Studies on genetic predisposition to cancer diseases revealed the existence of a number of founder alleles and recurrent mutations in several genes, including BRCA1, CHEK2, and PALB2 genes." (PMID 35313928, 2022). "Germline BRCA1/2 testing can be additionally advantageous if performed within a multigene panel that assesses other genes linked to cancer predisposition." (PMID 35735457, 2022). "As reported in a previous pan-cancer study, the biallelic pathogenic alterations of BRCA1/2 accounted for 68.7% of all cases harboring BRCA1/2 mutations, which increased to 89.9% in BRCA-associated cancers." (PMID 35578198, 2022). "Increased cancer susceptibility in the fallopian tube appears to begin with loss of a single allele of BRCA1 or BRCA2." (PMID 35159349, 2022). "YHP-836 inhibited cancer cell growth with BRCA1/2 mutation more effectively than those with wild type." (PMID 35910366, 2022). "The results suggest that the range of cancer types associated with pathogenic variants in BRCA1 and BRCA2 is likely broader than that determined from previous analysis of largely European ancestry cohorts." (PMID 35420638, 2022). "Accurately identifying pathogenic BRCA1 variants is crucial for ensuring patients and their families are presented with options to reduce their cancer risk." (PMID 38836089, 2022). "Given there is no basis on which to reliably predict a milder phenotype of reduced cancer risks or later-onset diagnosis, evidence-based BRCA1 risk ranges were provided to both patients, alongside standard clinical care for BRCA1 carriers." (PMID 36068545, 2022). "PARP-1 suppression enhances the damage of injured DNA resulting in synthetic lethality in DNA-repairing-deficient cancer cells, such as BRCA1/2-deficient cells." (PMID 35956876, 2022). "Our group has successfully demonstrated that the simultaneous targeting of PARP1 and RAD52 induces “dual synthetic lethality” in BRCA1/2-deficient cancer cells." (PMID 36497275, 2022). "A population-based study conducted in 32,247 women with BC screened for a panel of cancer predisposing genes found the majority of variants to occur in BRCA1 and BRCA2 genes." (PMID 36003761, 2022). "In this paper, we reviewed the association of BRCA1 with transcriptional regulatory G4s, considering recent advances on the cancer genome and fundamental cellular processes on DNA such as transcription and DNA replication." (PMID 35327946, 2022). "Recent studies also revealed that homologous recombination repair (HRR) plays a pivotal role in cell survival as demonstrated by the increased cytotoxicity of G4 binders in BRCA1/2-deficient cancer cells." (PMID 36114513, 2022). "It is reported that alteration of some DDR genes in cancers, including BRCA1, BRCA2, RAD51B, and RAD51C, is associated with therapy sensitivity." (PMID 36081518, 2022). "A clinically implemented synthetic lethality principle is based on the finding that cancer patients carrying BRCA1/2 mutations are sensitive to inhibition of PARP1." (PMID 36124865, 2022). "Supporting this observation, CST has been shown to promote ploy (ADP-ribose) polymerase inhibitor (PARPi) sensitivity in BRCA1-deficient cancer cells." (PMID 35368664, 2022). "Recently, the PARP inhibitor Olaparib has been evaluated as a promising anti-cancer agent in women with germline pathogenic variants in BRCA1 or BRCA2." (PMID 35563522, 2022). "We investigated the prevalence of PVs in BRCA1/2 and 23 other cancer predisposition genes using an overall study sample of 614 patients with mBC." (PMID 35805063, 2022).
cancer (continued). "Double-stranded break repair are defective in homologous recombination–deficient (HRD) cancer cells with BRCA1 or BRCA2 pathogenic variants (PVs)." (PMID 36577523, 2022). "PARP1 inhibition (PARPi) in BRCA1/2 mutated tumors has been successful in many types of cancers, including breast, ovarian, prostate, pancreatic, colon, and lung." (PMID 35800362, 2022). "Poly (adenosine diphosphate ribose) polymerase inhibitors (PARPis) have demonstrated antitumoral activity in several cancers harbouring germline and somatic BRCA1/2 mutations." (PMID 36139634, 2022). "Recently, growing evidence has demonstrated that inhibition of PARP is a promising targeted therapy for cancer patients with deficiency in BRCA1/2 or other DDR genes." (PMID 35719981, 2022). "PARP inhibitors are the first clinically approved anti-cancer agents which specifically targeted the DNA damage response in BRCA1/2-mutated cancers." (PMID 36233090, 2022). "Overall, we see the most significant epigenomic changes in BCs and SCs due to BRCA1 mutation among the four cell types from these pre-cancer breast tissue samples, while fewer variations were seen in LPs." (PMID 35118379, 2022). "Reversion mutations can restore BRCA1/2 function and result in treatment resistance in these cancer-types." (PMID 36418296, 2022). "In conclusion, a positive attitude towards physical activity seems to play a role in the current VO2peak status in cancer-unaffected and cancer-affected BRCA1/2 mutation carriers." (PMID 35190584, 2022). "Meta-analyses investigating the presence of BRCA genes in patients with cancer found that the missense variant was the most frequent in patients with BRCA1 and BRCA2 variants." (PMID 35251954, 2022). "Daily levels of progesterone were higher throughout the menstrual cycle of BRCA1/2 mutation carriers, raising the prospect of targeting progesterone signalling as a means of cancer risk reduction in this population." (PMID 35701800, 2022). "Synthetic lethality between PARP inhibitors and pathogenic germline mutations in BRCA1/2 is exploited for the treatment of HR-deficient cancers." (PMID 36350633, 2022). "PARPi is the first class of drugs used clinically to target HRD cancers via synthetic lethality and has been well studied in BRCA1/2 mutated cancers, including pancreas, prostate, breast, and ovarian, generally with very positive results." (PMID 35626165, 2022). "We frequently observed allelic deletions that are positioned in CFSs, which was more frequently observed in HR-deficient cancers when compared to HR-proficient cancers (19% vs 15%, p = 7.55E−11), and more frequently observed in BRCA1/2 mutant cancers." (PMID 36344511, 2022). "The most common mechanism responsible for the development of resistance to PARPi is the restoration of HR repair activity in BRCA1/2-mutated cancer cells." (PMID 36497275, 2022). "The PARP-1 inhibitors can selectively kill the cancer cells with homologous recombination (HR) defect caused by BRCA1/2 mutations, and have been approved for the therapy of cancers such as ovarian cancer, prostate cancer and breast cancer, etc." (PMID 36353483, 2022). "High cancer risks, as applicable to BRCA1 and BRCA2 pathogenic variant (PV) carriers, can induce significant cancer concerns." (PMID 34997316, 2022).
cancer (continued). "Our recent work suggests that CSB facilitates BIR-mediated restart of stalled forks and that this function of CSB promotes survival of cancer cells with deficiencies in either BRCA1 or BRCA2 in response to replication stress." (PMID 36142121, 2022). "We had expected that previously cancer-affected BRCA1/2 mutation carriers would reach their VO2peak reference value less often compared to the cancer-unaffected participants." (PMID 35190584, 2022). "In 2003, indications of PGT wereextended to late-onset or incomplete penetrance diseases, such as hereditary predisposition to cancer as BRCA1 or BRCA2 mutations." (PMID 36497251, 2022). "BRCA1/2 mutations were associated with a higher grade of disease when compared with other cancer‐associated gene mutations (p value = .006)." (PMID 35608067, 2022). "In this regard, synthetic lethality is proven a promising strategy to inhibit cancer cells that harbor deficient BRCA1 or BRCA2 genes." (PMID 35328658, 2022). "The mutated BRCA1 impairs its function of repairing double-strand DNA breaks, leading to genome instability, cellular transformation, and eventually cancer effecting mostly breast and ovarian." (PMID 35869059, 2022). "Precancerous cells deficient in BRCA1 and 2 cannot repair DSBs properly, resulting in genomic instability that eventually leads to cancer." (PMID 35785170, 2022). "Talazoparib monotherapy demonstrates a tolerable safety profile and preliminary clinical activity in patients with sporadic cancers harboring germline BRCA1/2 mutations." (PMID 36209184, 2022). "This approach has medical implications, establishing PARPi as potential drugs in BRCA1/2-mutated (BRCA1/2m) cancers, as has been validated both in vitro and in vivo." (PMID 36533080, 2022). "Identifying carriers of pathogenic BRCA1/BRCA2 variants reduces cancer morbidity and mortality through surveillance and prevention." (PMID 36551598, 2022). "We also examined the effects of ZKSCAN3 depletion on the sensitivity of BRCA1-deficient cells to Olaparib and cisplatin, both of which are used to treat BRCA1-deficient cancers." (PMID 35779634, 2022). "The SBS3 HR deficient signature has previously been associated with HRD and germline and somatic BRCA1 and BRCA2 mutations and BRCA1 promoter methylation in breast, pancreatic and ovarian cancers." (PMID 35637530, 2022). "The reverse was true for TRβ, with BRCA1-associated cancers that were positive for TRβ expression having a better prognosis than TRβ-negative counterparts." (PMID 35160139, 2022). "Recently, DHX9 has been found to participate in the recruitment of BRCA1 to RNA and promote DNA end resection in homologous recombination, as well as prevent R-loop-associated DNA damage and be overexpressed in cancer." (PMID 35814441, 2022). "To study the biology of BRCA1-associated cancers, we previously created a mouse model carrying a mammary tissue–specific deletion of the full-length form of BRCA1 using a Cre-loxP approach." (PMID 35025764, 2022). "For this reason, we did not observe the association between laterality of BC as well as personal cancer history and deleterious germline variants, including BRCA1/2." (PMID 36232564, 2022). "Mutations in BRCA1/2 are associated with a homologous recombination deficiency phenotype in BRCA-associated cancers." (PMID 36418296, 2022). "Investigating the BRCA1/2 mutational status in patients with OC is crucial not only for the identification of familial cancer predisposition, but also to address therapeutic choices." (PMID 36555431, 2022). "They exclusively produce synthetic toxicity in cancerous cells through homologous recombination deficiencies (HRDs), and one of the most prominent mechanisms is via mutations in the BRCA1/2 genes present in cancer cells." (PMID 35873570, 2022). "Mutations in BRCA1, which encodes breast cancer type 1 susceptibility protein (BRCA1), significantly increase the cancer incidence in several tissues." (PMID 35327946, 2022).
cancer (continued). "Reactivation of HR through secondary mutations or epigenetic regulation of BRCA1/2 is frequently identified and has been found in patients with ovarian, breast, pancreatic and prostate cancer with PARPi-resistant disease." (PMID 36284291, 2022). "It would be informative to see if expression of HSATII in EOC and other cancers is associated with specific patterns of chromosomal rearrangements or specific defects in BRCA1-related DNA repair pathways." (PMID 35968784, 2022). "Heterozygous mutations of BRCA1 lead to inherited breast cancer syndromes but are also seen in about 18% of ovarian cancers and represent a significant factor of risk for other cancers such as prostate cancers." (PMID 36551628, 2022). "The importance of BRCA1/2 and PALB2 in HRR and the benefit of PARPi in BRCA1/2 mutations are well characterized in multiple cancers, including PDAC." (PMID 35681599, 2022). "BRCA1/2-associated cancers were identified in 70.8% of patients (34/48, including two double-heterozygotes), with the majority (35.3%, 12/34) representing known South African founder variants." (PMID 36568162, 2022). "In two male patients BRCA1 mutations were found, and families were advised towards proper analysis and follow-up programs for family members at risk for cancer." (PMID 35572556, 2022). "BRCA1/BRCA2 screening offers an opportunity for primary prevention of cancer in unaffected carriers by risk-reducing mastectomy (RRM) and RRSO." (PMID 36551598, 2022). "Out of the total 7,919 samples containing 4,278 cancer patients and 3,641 cancer-free individuals, 729 were detected with BRCA1/2 deleterious germline mutations, of which 539 individuals carried BRCA1 mutations and 213 carried BRCA2 mutations." (PMID 35378767, 2022). "Several other proteins interact and cooperate with BRCA1/2 in the DNA repair process and can also be key factors in cancer susceptibility, particularly in BC and OC, that present a defect in the HR system." (PMID 36230639, 2022). "The previously best-known tissues exhibiting cancer susceptibility of BRCA1 are the breasts and ovaries." (PMID 35327946, 2022). "Women with a harmful BRCA1 mutation, which leads to loss of BRCA1 function, commonly develop cancers in hormonal responsive organs, such as breasts and ovaries." (PMID 34996912, 2022). "Such an outcome would lend further support to the potential use of autophagy inhibition to treat PALB2 and BRCA1 mutant cancers and possibly other cancers associated with DNA damage and oxidative stress." (PMID 40396054, 2022). "The excess mutational load in BRCA1–/– cells follows a specific pattern of base changes, with strong correlation to COSMIC signature SBS3, a hallmark phenotype of BRCA1 or BRCA2 mutated human cancers." (PMID 35130276, 2022). "Analysis of human cancer genome sequences has revealed specific mutational signatures associated with BRCA1-deficient tumors, but the underlying mechanisms remain poorly understood." (PMID 35879372, 2022). "Screening for founder pathogenic variants in BRCA1 revealed the presence of 5 out of 5 selected variants in 103 out of the 3,400 cancer patients and their selected relatives (3.03%)." (PMID 36171877, 2022). "The estimated age-specific risks will refine cancer risk management in men and women with BRCA1/2 PVs." (PMID 35077220, 2022). "In this study, we have only shown the prognostic contributions of BRCA1/2 mutations in OV cancers patients and patients with both BROV cancers." (PMID 35608067, 2022). "More importantly, PARP inhibitors (PARPi) revolutionised the field of precision medicine in cancer when they were demonstrated to selectively kill tumours bearing germline mutations in the HR-associated genes Breast Cancer gene 1 and 2 (BRCA1/2)." (PMID 36612003, 2022). "In 2005, two seminal studies demonstrated that cancer cells deficient in BRCA1 or BRCA2 exhibit selective and exquisite sensitivity to PARP inhibition." (PMID 35834102, 2022).
cancer (continued). "In this first study providing molecular data on BC in our country, among the 137 BC patients recruited at the only state cancer referring center, 38 (27.7%) carried a BRCA1/2 pathogenic or likely pathogenic variant." (PMID 35858847, 2022). "Recently, 138,342 eligible individuals in the Ambry Genetics patient database were examined for BRCA1/2 variant reclassification based on personal and family history of cancer." (PMID 36315513, 2022). "As clinical studies continue to delineate the role of PARPi in cancer therapy, this class of medications provides clinicians treating patients with germline BRCA1/2 variants a vast potential of clinical utility." (PMID 35685436, 2022). "Considering the complex interaction between PARP1, HR and other DNA damage repair pathways in the setting of BRCA1/2 mutated cancers, several different mechanisms of resistance have been proposed, although some of them have been only described preclinically." (PMID 35681784, 2022). "Maximum benefit was therefore gained to reduce their risk of developing cancer types associated with BRCA1/2 pathogenic variants." (PMID 35464868, 2022). "As an exemplar of the workflow and output of VaLiAnT we have generated oligonucleotide libraries suitable for performing SGE experiments on the exons encoding the RING domain of the tumour-suppressor gene BRCA1 (Breast cancer type 1 susceptibility protein)." (PMID 34791067, 2022). "In the present study, among 321 unrelated women with BC, the frequency of GPVs in BRCA1/2 genes was 9.6% and in non-BRCA1/2 cancer predisposition genes was 15.6%." (PMID 36119527, 2022). "Our study reveals multiple potential drivers of recurrent disease in BRCA1/2 mutation-associated cancer, improving our understanding of tumor evolution and suggesting potential biomarkers." (PMID 36344544, 2022). "Increasing time since BRCA1/2-PV diagnosis and being employed were significantly associated with lower cancer worry." (PMID 34997316, 2022). "In this study, we analyze matched tumor and normal sequencing from 31,927 patients and identify 846 (2.7%) patients with germline BRCA1/2 variants across 43 different cancer types, including 11 with somatic reversion mutations." (PMID 36418296, 2022). "On the basis of this result, currently, CX-5461 is in phase II/III clinical trial on BRCA1/2 mutated cells and BRCA1/2-deficient tumors (Canadian Cancer Trials Group ID: NCT02719997)." (PMID 35409143, 2022). "Cancer susceptibility in BRCA1 and BRCA2 mutation carriers has generally been attributed to increased chromosomal instability in BRCA1/2 deficient cells." (PMID 35017534, 2022). "Efficacy and safety of olaparib and durvalumab combination in patients with solid tumors were then assessed in the MEDIOLA phase 1/2 basket clinical trial (NCT02734004), in 32 patients with different types of cancer characterized by the same BRCA1/2 mutation." (PMID 36428727, 2022). "More than 80% of patients (n = 392) carrying an actionable BRCA1/2 variant reported family members affected with BC and other cancer types." (PMID 35464868, 2022). "We analyzed germline variants of BRCA1/2 genes for 2168 individuals who had cancer diagnosis or high risk assessment due to BRCAs related cancers, referred to 10 health care centers distributed across 7 regions covering the Turkish landscape." (PMID 35753294, 2022). "This study aimed to explore the subjective experiences and needs of the BRCA1/2 alteration population in navigating cancer risk reduction measures." (PMID 35933387, 2022). "To address outstanding questions about cancer recurrence in BRCA1/2 mutation carriers, we performed an analysis of paired primary and recurrent BRCA1/2 mutation-associated tumors." (PMID 36344544, 2022). "BRCA1/2-mutated cancers with abnormal DNA homogenous repair are vulnerable to further DNA repair pathway suppression." (PMID 35422863, 2022).